OR10J1 (olfactory receptor family 10 subfamily J member 1)
Description:
Odorant receptor.
Synonyms: HGMP07J; HSHGMP07J
Tractability: Antibody: its Gene Ontology location is reachable by antibodies, with high confidence; UniProt places it where antibodies can reach, with medium confidence; UniProt predicts a signal peptide or a membrane-spanning region.
Gene: Protein-coding gene on chromosome 1 (159,437,845 to 159,443,078, forward strand). Ensembl gene ENSG00000196184.
Subcellular location: Cell membrane
Pathways (Reactome):
Sensory Perception: Expression and translocation of olfactory receptors
Gene Ontology:
Molecular function: G protein-coupled receptor activity; odorant binding; olfactory receptor activity
Biological process: detection of chemical stimulus involved in sensory perception of smell; G protein-coupled receptor signaling pathway; sensory perception of chemical stimulus; single fertilization
Cellular component: membrane; plasma membrane
Genetic constraint (gnomAD): Loss-of-function variants: 1 observed, 0.27 expected, observed/expected ratio (o/e) 3.75. That is too few expected variants to judge how well the gene tolerates losing a copy. Missense variants: 474 observed, 395.85 expected, observed/expected ratio (o/e) 1.2, 90% interval 1.11 to 1.29. Synonymous variants: 202 observed, 152.41 expected, observed/expected ratio (o/e) 1.33, 90% interval 1.18 to 1.49.
Homologues: Orthologues: rabbit OR10J1 (91% identical), pig OR10J1 (86% identical). Paralogues in human: OR10J5 (72% identical), OR10J3 (63% identical), OR10Z1 (54% identical), OR10R2 (53% identical), OR10T2 (52% identical), OR10K1 (51% identical), OR10K2 (49% identical), OR10J4 (45% identical), OR1E1 (43% identical), OR1L1 (43% identical), OR7A10 (43% identical), OR7A17 (43% identical), and 116 more.